AHCYL2 (adenosylhomocysteinase like 2)
Description:
Regulatory protein that interacts with and modulates the activity of membrane ion transporters, including the sodium-bicarbonate cotransporter SLC4A4, through phosphorylation-dependent binding. Functions as a homolog of AHCYL1 to regulate bicarbonate transport and intracellular pH homeostasis via direct interactions rather than enzymatic activity (By similarity). On the contrary of its homolog AHCYL1, does not regulate ITPR1 sensitivity to inositol 1,4,5-trisphosphate.
Synonyms: IRBIT2; KIAA0828; long-IRBIT; ADOHCYASE3
Tractability: Small molecule: a structure with a bound ligand is known; it has a binding pocket of medium quality. PROTAC: ubiquitination databases record sites on it; its protein half-life has been measured.
Gene: Protein-coding gene on chromosome 7 (129,225,021 to 129,430,211, forward strand). Ensembl gene ENSG00000158467.
Subcellular location: Cytoplasm; Microsome
Subcellular location (Human Protein Atlas): Cytosol; Nucleoplasm; Vesicles
Pathways (Reactome):
Transport of small molecules: Bicarbonate transporters
Gene Ontology:
Molecular function: protein binding; adenosylhomocysteinase activity
Biological process: S-adenosylmethionine cycle
Cellular component: cytoplasm; cytosol
Genetic constraint (gnomAD): Loss-of-function variants: 26 observed, 69.98 expected, observed/expected ratio (o/e) 0.37, 90% interval 0.27 to 0.52. The upper end of that interval is the gene's LOEUF score, 0.52, which puts it in group 2 of 6, group 1 being the genes least tolerant of losing a copy. Missense variants: 524 observed, 694.45 expected, observed/expected ratio (o/e) 0.75, 90% interval 0.7 to 0.81. Synonymous variants: 259 observed, 256.28 expected, observed/expected ratio (o/e) 1.01, 90% interval 0.91 to 1.12.
Homologues: Orthologues: chimpanzee AHCYL2 (99% identical), dog AHCYL2 (99% identical), macaque AHCYL2 (99% identical), mouse Ahcyl2 (99% identical), pig AHCYL2 (99% identical), rabbit AHCYL2 (99% identical), rat Ahcyl2 (99% identical), guinea pig AHCYL2 (88% identical), tropical clawed frog ahcyl2 (87% identical), zebrafish ahcyl2b (85% identical), zebrafish ahcyl2a (66% identical), Drosophila melanogaster AhcyL1 (63% identical), and 1 more. Paralogues in human: AHCYL1 (76% identical), AHCY (36% identical).
Diseases named in the same sentence as AHCYL2 in open-access papers:
AHCYL2 is named in the same sentence as 16 diseases in open-access papers, as found by Europe PMC text mining. Sharing a sentence is not in itself a finding about the gene and the disease. The quoted sentences say what the papers report.
lung carcinoma (3 papers, 2019 to 2025). "Genes AHCYL2 and PSPN were reported to be associated with lung cancer." (PMID 31640538, 2019). "Other genes were reported in the context of other cancer types, e.g. AHCYL2 as having a potential role in melanoma, colorectal, ovarian, and lung cancer, and KCNS3 as potentially relevant in colon and lung cancers." (PMID 39825380, 2025).
colorectal cancer (1 paper, 2018). A primary or metastatic malignant neoplasm that affects the colon or rectum. "The methylation of five genes (AHCYL2, IL11RA, SEMA6D, BIRC3, and HADHB) was associated with tumors, and four genes (IL11RA, CHL1, SEMA6D, and BIRC3) were associated with colorectal cancer." (PMID 29507648, 2018).
colorectal tumour (1 paper, 2018). "PAFAH1B3 has been proposed as a driver cancer gene, while AHCYL2, which is highly expressed in the gastrointestinal tract, has been found to be highly downregulated in the gene expression profiling of colorectal tumour." (PMID 29304754, 2018).
meningioma (1 paper, 2020). A generally slow growing tumor attached to the dura mater. "Ten biomarkers, particularly AHCYL2, FGL2, and KCNMA1, were significantly related to grades and prognosis of meningioma." (PMID 32596316, 2020). "Though there were only four normal samples in GSE43290, the efficacy evaluation results still showed that five genes, including AHCYL2 (AUC = 0.729), FGL2 (AUC = 0.782), ID3 (AUC = 0.926), KCNMA1 (AUC = 0.745), and NMNAT2 (AUC = 0.851), could significantly distinguish meningiomas and normal samples." (PMID 32596316, 2020).
type 2 diabetes (1 paper, 2016). "Just like the polymorphism between EXOC4 and LRGUK, AHCYL2 is associated with type 2 diabetes." (PMID 27589727, 2016).
cancer (5 papers, 2018 to 2025). A tumor composed of atypical neoplastic, often pleomorphic cells that invade other tissues. "This gene has been linked to tumors, specifically showing associations between AHCYL2 and certain cancers." (PMID 38397233, 2024). "Studies have revealed correlations between AHCYL2 expression and tumor cell proliferation, angiogenesis, and poor prognosis in some cancers." (PMID 38397233, 2024). "Notably, SP1-enriched promoters were predominantly associated with known oncogenes, including Ahcyl2, Bcl3, and Sp1 itself, suggesting that SP1’s oncogenic potential may arise from its role in regulating transcription of cancer-associated genes." (PMID 40884402, 2025).
tumor (5 papers, 2018 to 2025). "For example, we have found that inhibition of AhcyL1 and AhcyL2, enzymes functioning in the methionine metabolic process, potently inhibits fly tumor growth." (PMID 40523311, 2025). "Significant hypermethylation of ODC1, MTHFR and AHCYL2 occured also in the tumor adjacent, histologically benign urothelial tissue samples." (PMID 29472622, 2018). "Interestingly, we found that knockdown of AhcyL1 and AhcyL2, which potentially elevates S-adenosyl homocysteine hydrolase Ahcy activity, elevated H3K9me3 levels and strongly inhibited dlg mutant tumor growth." (PMID 40523311, 2025). "Although panomics revealed low RNA and protein expression of CA1, CLCA1, MATN2, AHCYL2, and FCGBP in malignant tissues compared to healthy colon mucosa, no differentially expressed RNA or protein targets were detected between tumour and metastatic tissues." (PMID 36691026, 2023).
AHCYL2 also shares sentences with these, for which no sentence is quoted: colon carcinoma (1 paper); melanoma (1); Obesity (1); prostate carcinoma (1); rectum adenocarcinoma (1); renal carcinoma (1); stomach adenocarcinoma (1); thyroid carcinoma (1); uterine corpus endometrial carcinoma (1).